DPP7 (dipeptidyl peptidase 7)
Diseases named in the same sentence as DPP7 in open-access papers (continued):
Sharing a sentence is not in itself a finding about the gene and the disease.
tumor (13 papers, 2019 to 2025). "Given that tumour immune evasion is a major obstacle in cancer treatment, previous study has reported that DPP7 is associated with NK‐cell activity." (PMID 40576169, 2025). "To understand the potential mechanism that Tamarixetin inhibits CRC via DPP7 suppression, we performed GSEA analysis in the TCGA database and identified that DPP7 is closely associated with the activation of the WNT signalling pathway in CRC tumours." (PMID 40845164, 2025). "Dipeptidyl Peptidase 7 (DPP7) is highly associated with tumour progression, and the knockdown of DPP7 increases apoptosis in tumour cells." (PMID 40845164, 2025). "Knockdown DPP7 in TAMs restores the phagocytic ability of macrophages, thereby remodeling the immunosuppressive tumor microenvironment." (PMID 41208881, 2025). "On the other hand, DPP7 enhances the viability of tumour cells by promoting the progression of the cell cycle and inhibiting the DNA damage response." (PMID 40845164, 2025). "In vivo, DPP7 knockdown in bone marrow-derived macrophages (BMDMs) synergized with anti-PD-1 therapy, achieving significant suppression of subcutaneous xenograft tumor growth and liver metastatic burden by reversing the immunosuppressive TIME." (PMID 41208881, 2025). "Quantitative analysis demonstrated enhanced infiltration of DPP7+TAMs within tumor tissues compared to normal mucosa, with preferential accumulation in patients with metastatic lesions, which was corroborated by scRNA-seq analyses." (PMID 41208881, 2025). "Strikingly, the combination regimen exhibited the best anti-tumor efficacy, indicating the synergistic enhancement of PD-1 blockade through DPP7 suppression in BMDMs." (PMID 41208881, 2025). "To determine if GPX4 mediates the tumour‐promoting effects of DPP7, we conducted rescue experiments by overexpressing GPX4 in DPP7‐depletion cells." (PMID 40576169, 2025). "A particularly intriguing aspect of our study is the role of DPP7 in regulating NK cell‐mediated anti‐tumour immunity." (PMID 40576169, 2025). "Higher preoperative serum carcinoembryonic antigen (CEA) levels and larger tumor sizes were also observed in the high DPP7+TAMs group." (PMID 41208881, 2025). "The qPCR and Western blot results from 8 pairs of surgical specimens from the First Affiliated Hospital of Nanchang University also showed increased DPP7 expression in tumor tissues." (PMID 39247602, 2024). "We found that the knockdown of DPP7 in tumor cells increased the level of IL-2 in the co-culture system, while overexpression of DPP7 decreased the level of IL-2 in the medium." (PMID 39247602, 2024). "We suspected that overexpression of DPP7 in tumor cells would accelerate T-cell exhaustion in the co-culture microenvironment." (PMID 39247602, 2024). "In CRC, we analyzed mRNA expression data for paired samples (from the same patients) and unpaired samples, revealing a significant upregulation of DPP7 expression in tumor tissues (P < 0.001)." (PMID 39247602, 2024). "In summary, high expression of DPP7 in tumor cells increases the expression of PD-1 in activated THP-1 cells in the co-culture system." (PMID 39247602, 2024). "Immune infiltration analysis and co-culture results indicate that overexpression of DPP7 suppresses the immune cell's cytotoxic function against tumors in the tumor microenvironment." (PMID 39247602, 2024). "We further constructed a nomogram incorporating the expression level of DPP7 and another three clinicopathologic variables including age, lymphatic invasion, and residual tumor." (PMID 37568770, 2023). "We identified KEAP1 and DPP7 as genes controlled by H3K9ac in response to heat shock that can better induce apoptosis in tumor cells when combined with hyperthermia." (PMID 37781518, 2023). "A point scale was used to assign these variables to the nomogram based on multivariate Cox analysis (age, lymphatic invasion, residual tumor, and DPP7 expression)." (PMID 37568770, 2023).
tumor (continued). "In this study, we identified two genes, KEAP1 and DPP7, that showed significant tumor growth delay and enhanced tumor cell apoptosis only when overexpressed in combination with hyperthermia." (PMID 37781518, 2023). "Our results suggest that the combination of KEAP1 and DPP7 with hyperthermia treatment can more effectively inhibit tumor cell growth and induce tumor cell apoptosis." (PMID 37781518, 2023). "KEAP1 and DPP7 as genes affected by heat-induced inhibition of H3K9ac, and combining them with hyperthermia can better induce apoptosis in tumor cells." (PMID 37781518, 2023). "The mRNA of DPP7 was highly expressed in the CRC tumor tissues (n = 619) compared with the normal tissues (n = 51, p < 0.001)." (PMID 37568770, 2023). "Furthermore, IHC validation confirmed both the upregulation of DPP7 in tumor and its positive correlation with CD68 expression." (PMID 41208881, 2025). "In addition, tumor growth suppression mediated by DPP7 knockdown was abrogated following CD8+T cell depletion." (PMID 41208881, 2025). "To validate whether DPP7/WNT3A/β‐catenin pathway is essential for the anti‐tumour effect of Tamarixetin, we examined the proliferation of DPP7 overexpressing cells after the treatments." (PMID 40845164, 2025). "However, our analysis of immune cell infiltration revealed a correlation between DPP7 expression in tumor cells and cytotoxic T cells, which seems difficult to comprehend." (PMID 39247602, 2024). "Therefore, we used activated THP-1 cells to investigate the relationship between tumor DPP7 expression and PD-1." (PMID 39247602, 2024). "Study the Impact of DPP7 on malignant progression and tumor immunity in CRC." (PMID 39247602, 2024). "In summary, high expression of DPP7 may mediate immune escape by inhibiting the anti-tumor ability of Jurkat cells in the co-culture microenvironment." (PMID 39247602, 2024). "Therefore, we constructed a co-culture model composed of activated Jurkat cells, HCT116, and SW480 cells to investigate the effect of tumor cells' DPP7 expression on the killing function of activated Jurkat cells." (PMID 39247602, 2024). "Finally, the impact of DPP7 on cell proliferation, invasion, migration, and immune cell function in the tumor microenvironment was confirmed through cell experiments and animal studies." (PMID 39247602, 2024). "Although the results of this study indicate a positive correlation between DPP7 expression and NK cells in the tumor microenvironment, NK cells will face considerable challenges in exerting anti-tumor effects in the tumor microenvironment due to the factors above." (PMID 39247602, 2024). "Moreover, co-culture experiments of tumor cells with immune cells confirmed the impact of DPP7 expression in tumor cells on immune cell function." (PMID 39247602, 2024). "Still, the results showed that when DPP7 expression in tumor cells was elevated, the cytotoxic function of activated Jurkat cells was inhibited, leading to decreased secretion of the immune cytotoxicity marker IL-2 on the one hand, and decreased viability of Jurkat cells on the other hand." (PMID 39247602, 2024). "Finally, a series of experiments were conducted to investigate the effects of altering DPP7 expression on tumor cell proliferation, invasion, and migration." (PMID 39247602, 2024). "Excess dietary iron in tumor tissues was also associated with significant changes (generally, increases; p ≤ 0.05) in proteins involved in modulating cell protein integrity (HSPA5, HSPA9, ITGB1, PSMA4, DPP7, and PEPD), cell mobility and growth (CAPZB), and immunologic factors (FCGBP)." (PMID 38732562, 2024). "Currently, there is a controversy regarding whether KEAP1 and DPP7 can act as tumor suppressors." (PMID 37781518, 2023). "Functional studies revealed that DPP7 promotes CRC cell proliferation and survival while suppressing NK cell‐mediated cytotoxicity against tumour cells." (PMID 40576169, 2025).
tumor (continued). "Functional analyses revealed that DPP7 promotes CRC cell proliferation and inhibits apoptosis, while its depletion enhances natural killer (NK) cell‐mediated cytotoxicity against tumour cells." (PMID 40576169, 2025). "Overexpression of DPP7, on the other hand, promoted invasion and migration of these two tumor cells, and the expression of EMT-related proteins was the opposite of that of knockdown of DPP7." (PMID 39247602, 2024). "The public dataset and analysis of the biospecimens of CRC patients revealed that DPP7, in the CRC samples, was expressed significantly higher than in non-tumor tissues." (PMID 37568770, 2023). "DPP7, CDR2L exhibited higher and UNC5C, RAB3B, SLC18A2, GPRASP1, PCDH9 exhibited lower expression in tumor tissues (P<0.05)." (PMID 37384293, 2023). "DPP7-knockdown BMDMs demonstrated significant potent anti-tumor effects in immunocompetent C57BL/6J mice, but not in T cell-deficient Balb/c nude mice." (PMID 41208881, 2025). "Taken together, DPP7+TAMs in the CRC TIME generally exhibit an immunosuppressive function, and may play a pivotal role in promoting tumor mainly by promoting immunosuppressive cells, especially exhausted CD8+T cells." (PMID 41208881, 2025). "Initially, we compared DPP7 expression levels in tumor tissues and adjacent non-cancerous tissues within the TCGA dataset." (PMID 39247602, 2024). "The question of whether DPP7 regulates TAN activation and immune regulation in the early tumor stages of CRC needs further study and verification." (PMID 37568770, 2023). "We found that DPP7 was expressed higher in the tumor range than in the paired adjacent non-tumor tissues, and the increased expression of DPP7 predicted shorter overall survival." (PMID 37568770, 2023). "Within tumor tissue in the adequate iron group, and more so in tumors from the excess iron diet group, we found there was also significantly greater (p ≤ 0.05) expression of proteins involved in protein degradation (ANPEP, DPP7, ITGB1, PSMA1, PSMA2, PSMA3, and SERPINB1)." (PMID 38732562, 2024).
cancer (11 papers, 2021 to 2025). A tumor composed of atypical neoplastic, often pleomorphic cells that invade other tissues. "Although DPP7 has been reported to be associated with disease and cancer, the prognostic value and the potential function of DPP7 in CRC and the connection between DPP7 and the immune landscape remain unclear." (PMID 37568770, 2023). "Moreover, the increased expression of DPP7 is correlated with a higher stage of cancer and shorter overall survival, indicating the diagnostic value of DPP7 for CRC." (PMID 37568770, 2023). "Unlike its well‐characterised family member DPP4, which has been extensively studied in cancer biology, the role of DPP7 in tumorigenesis remains largely unexplored." (PMID 40576169, 2025). "Our study provides the first evidence linking DPP7 to the regulation of disulfidptosis in cancer cells." (PMID 40576169, 2025). "Furthermore, Western blot analysis indicated a significant upregulation of DPP7 expression in cancer cells such as HCT116, SW480, and SW620." (PMID 39247602, 2024). "DPP7 is known to be correlated with disease and cancer, but the prognostic value of DPP7 in CRC remains unclear." (PMID 37568770, 2023). "Several studies have explored the prognostic value of DPP7 in cancers." (PMID 37568770, 2023). "Recently, an increasing number of studies have revealed the alteration of DPP7 in various cancers and that inhibiting DPP7 may efficiently increase the apoptosis of cancer cells." (PMID 37568770, 2023). "Comparatively, DPP7 may play different prognostic roles in different cancer types, and our study first clarified the prognostic value of DPP7 as a single gene in CRC." (PMID 37568770, 2023). "On this basis, DPP7 targeting may improve treatment for a variety of cancer types, including CRC." (PMID 40845164, 2025). "The role of DPP7 in cancers, including ccRCC, is largely unknown." (PMID 36604669, 2023). "Our findings will further elucidate the mechanisms by which targeting DPP7 interrupts WNT/β‐catenin signalling, providing a theoretical basis for the application of Tamarixetin in CRC cancer." (PMID 40845164, 2025). "Consistent with results obtained from the TCGA-COAD cohort, six CRGs, including DPP7, GPRASP1, UNC5C, RAB3B, PCDH9, SLC18A2, were significantly downregulated, whereas CDR2L was upregulated in cancer tissues in comparison with paracancerous normal tissues." (PMID 37384293, 2023). "We also identified the top 1 GEAR in individual cancer types, such as TLL1 (BLCA), PGK1 (BRCA), RFXANK (CESC), DPP7 (COAD), VWA8 (KIRC), SCMH1 (LGG), HILPDA (LIHC), TLE1 (LUAD), CD151 (LUSC), ANKRD13A (OV), SOCS2 (PAAD), DRG2 (PRAD), ADAMTS6 (STAD), PSMB8 (THCA), ASS1 (UCEC)." (PMID 41404730, 2025).
DPP7 also shares sentences with these, for which no sentence is quoted: type 2 diabetes mellitus (2 papers); brain inflammation (1); coronary atherosclerosis (1); dementia (1); Hepatic steatosis (1); immune deficiency (1); ischemia (1); liver fibrosis (1); Niemann-Pick type C disease (1); non-alcoholic steatohepatitis (1); Parkinson disease (1); periodontitis (1); Prader-Willi syndrome (1); Reticulocytopenia (1); rheumatoid arthritis (1); systemic lupus erythematosus (1).